MCM6 (minichromosome maintenance complex component 6)
Diseases named in the same sentence as MCM6 in open-access papers (continued):
Sharing a sentence is not in itself a finding about the gene and the disease.
tumor (continued). "In addition, studies have shown that MCM6 in HCC indicates poor tumor characteristics and poor prognosis and promotes cell cycle progression, which is consistent with our study." (PMID 34022962, 2021). "Over a series of gain-of-function and rescue experiments, the results revealed that the methylation-dependent repression of MCM6 due to LINC00472 mediation was the potential mechanism substantiating the anti-tumor and anti-metastatic properties of LINC00472 in TNBC." (PMID 33668040, 2021). "The increase in MCM2, MCM3, and MCM6 is related to poor performance of the tumor." (PMID 33234725, 2020). "Harrell C-index could also proved that postoperative serum MCM6 not only significantly correlated with tumor early recurrence but also displayed improved indices of prognostic performance." (PMID 29357919, 2018). "Elevated MCM2, MCM6 and MCM7 were associated with adverse tumor features and poorer outcomes." (PMID 29463213, 2018). "Average expression level of MCM6 increases with the increasing tumor stages." (PMID 23874974, 2013). "Furthermore, MCM6 deficiency sensitized GC cells to chemo- or radiotherapy by causing DNA breaks and blocking ATR/Chk1-mediated DNA damage response (DDR), leading to exacerbated cell death and tumor regression." (PMID 36185598, 2022). "Moreover, the expression of MCM6 is different in different INSS tumor stages." (PMID 34233647, 2021). "Moreover, MCM4 and MCM6 expression are clinically relevant to tumor stage." (PMID 32021565, 2020). "Additional members of the MCM complex (i.e. MCM2, MCM3, MCM6, and MCM7) were upregulated in all sample groups but basal-like TN tumours." (PMID 36220861, 2022). "Since the restoration of MCM6 weakened the tumor-suppressive effect of LINC00472 on MDA-MB-231 cells, LINC00472 potentially acted as a tumor suppressor by inhibiting MCM6." (PMID 33668040, 2021). "It was also reported that MCM6 increases the proliferative and migratory/invasive capability of HCC cells in vitro, in addition to increasing the tumor volume, weight, and the number of pulmonary metastases in vivo." (PMID 32213663, 2020). "In particular, patients with dual positivity of postoperative serum MCM6 and AFP should be supplied with more intensive care and close follow-up after they undergo tumor resection." (PMID 29357919, 2018). "MCM2, MCM6 and MCM7 proteins were expressed at significantly higher levels in HCC compared to non-tumor specimens (P < 0.01), and the degree of their immunoreactivity gradually increased from normal and cirrhotic livers to HCC." (PMID 29463213, 2018). "To evaluate the expression of MCM6 in HCC tissues, we first conducted immunohistochemistry assay in 70 HCC specimens (tumor and matched adjacent non-tumorous tissues) and 30 normal hepatic tissue specimens." (PMID 29357919, 2018). "Bcl2, VEGFA, PTEN, Jun, Fos, APC2 were up-regulated and Ccna2, Cdc25a, Mcm3, Mcm6, Ccnb2, Mcm5, Cdk1, Gadd45a, Myc were down-regulated in MMQ tumor stem-like cells group." (PMID 28163656, 2017). "In the pathway in cell cycle, we found that the expression of Ccna2, Cdc25a, Mcm3, Mcm6, Ccnb2, Mcm5, Cdk1, Gadd45a were down-regulated in the MMQ tumor stem-like cells." (PMID 28163656, 2017). "From the results, we noticed that tumor cells highly expressed AUP1 significantly correlated with proliferation marker (MCM2, MCM6), PI3K-AKT-MTOR pathway (Akt1, TSC1, mTOR, Foxo1), and autophagy signaling (Atg3, Atg4B, Atg4D, Atg7, Atg9A, Atg16L1) in IDH wildtype tumor cells." (PMID 37029364, 2023). "In contrast, MCM6-expressing cells only existed in the isthmus of adjacent non-tumor tissue, a region enrichment of proliferating cells which were PCNA-positive." (PMID 36185598, 2022). "The binding of MCM6 to Cdt1, another component of the pre-replication complex, is the key to promoting the loading of the MCM complex on the chromatin for replication permission, so it is a potential marker for tumor diagnosis and treatment." (PMID 34233647, 2021).
tumor (continued). "The analysis on tumor growth, size and weight revealed that the LINC00472 overexpression resulted in smaller tumor size and weight, both of which were increased by upregulation of MCM6 (p < 0.05)." (PMID 33668040, 2021). "The data indicated that the MCM6 expression score in the nucleus was significantly lower in these nontumor tissues than in the respective tumor tissues." (PMID 31528213, 2019). "Furthermore, knockdown of MCM6 significantly decreased proliferative and migratory/invasive capability of HCC cells in vitro, as well as decreased tumor volume, weight and the number of pulmonary metastases in vivo." (PMID 29357919, 2018). "Furthermore, univariate analysis revealed that tumor size, GGT level, vascular invasion, early recurrence and MCM6 expression were unfavorable predictors for TTR and OS." (PMID 29357919, 2018). "We found a significant increase in MCM2 (3.5 fold), MCM3 (3.1 fold), MCM4 (4.3 fold), MCM5 (3.8 fold), MCM6 (3.5 fold), MCM7 (3.0 fold) and MCM10 (3.6 fold) expressions in tumor tissues (the average fold value of three grades) compared to the normal brain controls." (PMID 25046975, 2014). "Frequency of MCM6 over expression increases with advancement of the disease as, this gene is over expressed in 16% cases of stage I, 40% cases of stage II, and 40.6% cases of stage III of the tumor." (PMID 23874974, 2013). "For example, the MCM protein family (including MCM4, MCM6, and MCM3) plays a key role in DNA replication and cell cycle regulation and may affect tumor immune infiltration by affecting the proliferation and growth of tumor cells." (PMID 39083127, 2024). "MCM5 (40%), MCM6 (45.5%) and MCM9 (25%) were moderately higher in tumor tissues than in normal tissues, and MCM10 was negative in most (91.7%) tumor tissues." (PMID 34859821, 2021). "We detected high expression of MCM6 in 50/70 (71.4%) HCC tissues, compared with only 8/70 (11.4%) adjacent non-tumor tissues and no staining in normal tissues (P < 0.01)." (PMID 29357919, 2018). "Not all but some of the genes as MCM4, MCM6, MCM10 and RECQL4 show a positive trend with increasing tumor stages." (PMID 23874974, 2013). "The results demonstrated that CDK5RAP3 and MCM6 colocalized in the cytoplasm in the adjacent nontumor tissues, while CDK5RAP3 had lowered expression in the tumor tissues, and MCM6 had greater nuclear expression in tumor tissues." (PMID 31528213, 2019).
infection (4 papers, 2016 to 2023). The state of being infected such as from the introduction of a foreign agent such as serum, vaccine, antigenic substance or organism. "This is exemplified by the expression pattern of the proliferation markers Ki67 (Mki67), Pcna, Ccna2 and the minichromosome maintenance complex genes Mcm2 and Mcm6, which peak late in infection (Cell Cycle panel)." (PMID 38107402, 2023). "MCM complexes were depleted by infection with lentiviruses expressing short hairpin RNAs (shRNAs) targeting Mcm6 (shMcm6), with an shRNA against LacZ (β-Galactosidase) (shLacZ) serving as a control for infection and shRNA expression." (PMID 38081811, 2023). "Pf. minichromosome maintenance complex subunit 6 (MCM6), a helicase that is essential for DNA replication, is downregulated by -2.61 ± 0.27 fold on day 3 post-infection of hepatocytes." (PMID 27911910, 2016).
adenocarcinoma (3 papers, 2019 to 2024). A common cancer characterized by the presence of malignant glandular cells. "In our study, pHuR nuclear expression was significantly decreased in grade 3 compared to grade 1 adenocarcinomas, was correlated with better OS, and was inversely correlated with the expression levels of markers of proliferation MCM6 and Ki67." (PMID 38256026, 2024). "In our study, mHuR cytoplasmic expression was significantly decreased in grade 3 compared to grade 1 adenocarcinomas, was correlated with better OS, and was inversely correlated with the expression levels of markers of proliferation MCM6 and Ki67." (PMID 38256026, 2024). "Furthermore, in young patients (≤65 years) with histologically graded G2 adeno carcinoma, MCM6 expression levels above the cut-off also demonstrated a significant marker for a beneficial outcome." (PMID 31072339, 2019). "Among these differentially expressed proteins, MCM6, LCN2 and PADI4 were highly expressed in SOL adenocarcinomas and the high expression of which was correlated with poor OS." (PMID 38182978, 2024).
neurodevelopmental disorder (1 paper, 2023). A behavioral and cognitive disorder with onset during the developmental period that involves impaired or aberrant development of intellectual, motor, or social functions. "Taken together, our findings implicate de novo MCM6 variants in neurodevelopmental disorders." (PMID 37198333, 2023).
MCM6 also shares sentences with these, for which no sentence is quoted: endometrioid endometrial adenocarcinoma (4 papers); endometrial cancer (3); epilepsy (2); lung squamous cell carcinoma (2); viral infection (2); cervical squamous cell carcinoma (1); Chlamydia infection (1); cholangiocarcinoma (1); colon adenocarcinoma (1); craniopharyngioma (1); diabetes (1); endometrial adenocarcinoma (1); endometrial mixed adenocarcinoma (1); endometrial serous adenocarcinoma (1); esophageal neoplasm (1); esophageal squamous cell carcinoma (1); Fanconi anemia (1); glioblastoma multiforme (1); heart disease (1); Hypertonia (1); in situ carcinoma (1); irritable bowel syndrome (1); kidney chromophobe (1); leiomyosarcoma (1); leukaemia (1); liposarcoma (1); liver disease (1); lung adenocarcinoma (1); malignant fibrous histiocytoma (1); microcephaly (1).
A further 15 diseases each share a sentence with MCM6 in 1 paper.